GHRL (ghrelin and obestatin prepropeptide)
Diseases named in the same sentence as GHRL in open-access papers (continued):
Sharing a sentence is not in itself a finding about the gene and the disease.
gastric adenocarcinoma (2 papers, 2023 to 2024). "Western blotting also showed high expression of SPINK4, TTR, PCSK1N, CHGA and GHRL in gastric adenocarcinoma cell lines, with GHRL showing the most significant increase (p < 0.05)." (PMID 38752750, 2024). "CCK8 assay was performed to assess the activity of gastric adenocarcinoma cell lines upon GHRL knockdown." (PMID 38752750, 2024). "Our study using a gastric adenocarcinoma cell line model revealed a high expression of GHRL in gastric adenocarcinoma cells." (PMID 38752750, 2024). "It was evident that inhibiting GHRL significantly suppressed the invasive capacity of gastric adenocarcinoma cell lines." (PMID 38752750, 2024). "GHRL (Ghrelin) is a hormone that is highly expressed in gastric adenocarcinoma and is involved in tumour development by binding to its receptor, GHSR." (PMID 38752750, 2024). "According to the GEPIA database, we discovered that GHRL expression level was increased in diffuse large b-cell lymphoma and acute myeloid leukemia but was decreased in stomach adenocarcinoma (STAD) compared with healthy tissues." (PMID 37469414, 2023). "However, we observed that interference with GHRL significantly inhibited M2 polarization of macrophages, suppressed their invasion ability, and slowed down the progression of gastric adenocarcinoma." (PMID 38752750, 2024). "In summary, the GHRL gene may affect the pathogenesis of gastric adenocarcinoma by regulating M2 macrophage polarization." (PMID 38752750, 2024). "The GHRL gene may influence the pathogenesis of gastric adenocarcinoma by modulating M2 macrophage polarization and regulating the activity of macrophages and changes in the tumour microenvironment." (PMID 38752750, 2024). "GHRL gene may also participate in regulating the development and progression of gastric adenocarcinoma by influencing epithelial–mesenchymal transition and epigenetic regulation, and affecting the epithelial and mesenchymal characteristics of tumour cells." (PMID 38752750, 2024). "In summary, molecules such as DKK1, GHRL, STC1, NRP1 and ITGAV play important roles in the development and prognosis of gastric adenocarcinoma." (PMID 38752750, 2024). "Inhibiting the expression of GHRL in AIDPS significantly suppresses the activity of gastric adenocarcinoma cell lines and inhibits the transition of macrophages to the M2 polarization state, thereby slowing the progression of gastric adenocarcinoma." (PMID 38752750, 2024). "To investigate whether inhibiting GHRL expression affects the proliferative activity of gastric adenocarcinoma cell lines, firstly, we constructed stabilized cell lines of AGS and SGC‐7901 that silenced GHRL and detected the expression of GHRL by qRT‐PCR." (PMID 38752750, 2024).
hepatocellular carcinoma (2 papers, 2015 to 2025). A malignant tumor that arises from hepatocytes. "The ability of GhRL to stimulate proliferation has also been demonstrated in various cells and tissues, including osteoblasts, adrenocortical cells, cardiomyocytes and several types of cancer cell lines such as prostate hepatoma and colon." (PMID 39852916, 2025). "Genetic variations in the GHRL gene may play an important role in the development of chronic hepatitis B (CHB), liver cirrhosis (LC) and hepatocellular carcinoma (HCC)." (PMID 26599409, 2015).
Insulin resistance (2 papers, 2021 to 2026). Increased resistance towards insulin, that is, diminished effectiveness of insulin in reducing blood glucose levels. "Moreover, increased ghrelin (GHRL) levels were associated with improved insulin sensitivity, consistent with previous findings that ghrelin attenuates insulin resistance in women with PCOS." (PMID 41514462, 2026). "Additionally, elevated ghrelin (GHRL) levels post-acupuncture correlated with improved insulin sensitivity, consistent with studies linking GHRL to insulin resistance mitigation in PCOS." (PMID 41514462, 2026).
lung carcinoma (2 papers, 2019 to 2023). "Ghrelin, a widely distributed peptide hormone, participates in a series of cancer progression; GHRL plays a vital role in carcinogenic potential, which was correlated with breast cancer, lung cancer, bladder cancer, and adrenal cancer." (PMID 37469414, 2023).
non-Hodgkin lymphoma (2 papers, 2014 to 2023). Distinct from Hodgkin lymphoma both morphologically and biologically, non-Hodgkin lymphoma (NHL) is characterized by the absence of Reed-Sternberg cells, can occur at any age, and usually presents as a localized or generalized lymphadenopathy associated with fever and weight loss. "In addition, polymorphisms in the gene encoding the neuropeptide GHRL have been associated with non-Hodgkin lymphoma." (PMID 37444135, 2023).
ovarian carcinoma (2 papers, 2008 to 2022). A malignant neoplasm originating from the surface ovarian epithelium. "However, total GHRL RNA levels were higher than GHRLOS in the pancreas and the OVCAR-3 ovarian cancer cell line." (PMID 18954468, 2008).
schizophrenia (2 papers, 2012 to 2022). A major psychotic disorder characterized by abnormalities in the perception or expression of reality. "The positive symptoms of schizophrenia are associated with dysfunction in dopaminergic signaling, which is closely associated with a GHRL mutation." (PMID 22369141, 2012). "In addition to GHRL, this region contains SYN2, HRH1, and GRM7, all candidate genes for schizophrenia." (PMID 22369141, 2012).
Abdominal obesity (1 paper, 2023). Excessive fat around the stomach and abdomen. "Rare missense variants rs139997338 and rs760055038 were found in the GHRL gene in one case in patients with abdominal obesity." (PMID 37888112, 2023).
anorexia nervosa (1 paper, 2025). A disorder most often seen in adolescent females characterized by a refusal to maintain a minimally normal body weight, an intense fear of gaining weight, a disturbance in body image, and, in postmenarcheal females, the development of amenorrhea. "Randomized controlled trials (RCTs) have demonstrated that GHRL agonists significantly accelerate gastric emptying and increase body weight in women with anorexia nervosa." (PMID 40813643, 2025).
atherosclerosis (1 paper, 2025). A disease characterized by the build-up of fatty material and calcium deposition in the arterial wall resulting in partial or complete occlusion of the arterial lumen. "GHRL-specific receptors are present in cardiomyocytes, where GHRL enhances endothelial and vascular function, prevents atherosclerosis, and inhibits cardiac remodeling." (PMID 40813643, 2025). "Beyond its effects on appetite, GHRL plays a key role in various physiological processes, such as enhancing endothelial and vascular function, preventing atherosclerosis, inhibiting cardiac remodeling, and regulating anti-inflammatory, anti-apoptotic, and lipid metabolism pathways." (PMID 40813643, 2025).
breast tumor (1 paper, 2022). "Although a precise role for GHRL in BC has not yet been established, it has been suggested that an imbalance in the expression of the GHRL system in mammary tissue could be implicated in breast tumor pathogenesis." (PMID 35115550, 2022).
chondrosarcoma (1 paper, 2008). A malignant cartilaginous matrix-producing mesenchymal neoplasm arising from the bone and soft tissue. "The levels of GHRLOS expression were higher than GHRL in the thymus, whole brain, the SW1353 chondrosarcoma cell line, uterus and prostate." (PMID 18954468, 2008).
chronic heart failure (1 paper, 2025). "Additionally, clinical studies indicate that high plasma GHRL levels serve as a positive prognostic indicator in chronic heart failure (CHF), with plasma GHRL negatively correlated with NT-proBNP levels and positively correlated with left ventricular ejection fraction (LVEF)." (PMID 40813643, 2025).
chronic periodontitis (1 paper, 2017). A chronic inflammatory process that affects the tissues that surround and support the teeth. "Another study has shown elevated plasma levels of GHRL in patients with chronic periodontitis, as compared with periodontally healthy individuals." (PMID 29317796, 2017). "Interestingly, GHRL levels in GCF from patients with chronic periodontitis were lower than those from healthy individuals." (PMID 29317796, 2017).
COVID-19 (1 paper, 2025). A disease caused by infection with severe acute respiratory syndrome coronavirus 2. "This suggests that TOLLIP, TNFRSF4, AGER, and GHRL are crucial inflammatory COVID-19 markers." (PMID 40362649, 2025).
cyst (1 paper, 2026). A sac-like closed membranous structure that may be empty or contain fluid or amorphous material. "By bringing serum LEP levels back to normal and increasing those of GHRL, C. citratus inhibited the stimulus (hyperandrogenism) that dictates cyst formation in favor of ovarian follicle development and maturation." (PMID 41532033, 2026).
drug dependence (1 paper, 2013). "Since the heritability factor underlying drug dependence is shared between different drugs of abuse, we here examine the association between single nucleotide polymorphisms (SNPs) and haplotypes in the GHRL and GHSR, and amphetamine dependence." (PMID 23579732, 2013).
dyspepsia (1 paper, 2022). An uncomfortable, often painful feeling in the stomach, resulting from impaired digestion. "Studies have shown that stimulation of acupoint Zusanli(ST36) in rats could reduce the gastrointestinal hormone levels of ghrelin (GHRL), peptide YY(PYY), and glucagon-like peptide-1 (GLP-1), contributing to the amelioration of dyspepsia induced by cisplatin." (PMID 36304134, 2022).
dysplasia (1 paper, 2023). A usually neoplastic transformation of the cell, associated with altered architectural tissue patterns. "We also found that the expression of GHRL in dysplasia was significantly lower than that in CNAG and in GC." (PMID 37469414, 2023). "We found that the expression of GHRL in GC was higher than that in dysplasia (LGIN+HGIN), and the expression of GHRL in dysplasia was significantly lower than that in CNAG." (PMID 37469414, 2023).
hepatitis C (1 paper, 2015). "The findings of these researchers showed that the GHRL rs34911341 A allele was associated with HCC risk in patients with hepatitis C. Nonetheless, these studies were both performed with a small sample size and only focused on patients with HCV-related diseases." (PMID 26599409, 2015).
hyperandrogenism (1 paper, 2026). Excessive secretion of androgens from the adrenal glands or gonads. "Hyperandrogenism is also known to reduce GHRL production and increase LEP production." (PMID 41532033, 2026). "In conclusion, AE and HEE of C. citratus corrected PCOS‐induced ovarian follicular atresia in rats by reducing hyperandrogenism and modulating LEP and GHRL production." (PMID 41532033, 2026).
liver diseases (1 paper, 2015). "Only two studies to date have examined the association of GHRL polymorphisms with the risk of liver diseases." (PMID 26599409, 2015). "Until now, there were only two studies that examined the association between GHRL polymorphisms and the risk of liver diseases." (PMID 26599409, 2015). "Therefore, this study aimed to investigate whether SNPs rs26311, rs27647, rs696217, and rs34911341 of the GHRL gene and serum GHRL levels are associated with the risk to Chinese patients with HBV-related liver diseases." (PMID 26599409, 2015).
malnutrition (1 paper, 2025). Inadequate nutrition resulting from poor diet, malabsorption, or abnormal nutrient distribution. "Furthermore, the proposed inflammation-GHRL/MSTN-appetite improvement/muscle growth-CHF improvement pathway offers a potential regulatory mechanism,which represents a promising direction for research into the mechanisms of malnutrition and muscle loss disorders in patients with CHF." (PMID 40813643, 2025). "In clinical practice, we further revealed the relationship between GHRL, MSTN, CRP, and Hs -CRP through correlation analysis, aiming to further elucidate the potential pathophysiological mechanisms between malnutrition/sarcopenia and inflammation." (PMID 40813643, 2025). "Additionally, this study will compare the correlations between GHRL, MSTN, C-reactive protein (CRP), and high-sensitivity C-reactive protein (Hs-CRP), to further elucidate the potential relationship between malnutrition/muscle wasting disease and inflammatory pathophysiological mechanisms." (PMID 40813643, 2025).
periodontitis (1 paper, 2017). An acute or chronic inflammatory process that affects the tissues that surround and support the teeth. "Briefly, GHRL levels in gingival crevicular fluid (GCF) have been found lower in periodontitis patients when compared with healthy subjects." (PMID 29317796, 2017). "Until now, only a few studies have focused on the role of GHRL in periodontitis to explore whether GHRL may be involved in the regulation of periodontal inflammatory responses." (PMID 29317796, 2017).
cancer (12 papers, 2008 to 2025). A tumor composed of atypical neoplastic, often pleomorphic cells that invade other tissues. "The peptide hormone GHRL, in addition to having a role in the regulation of feeding and energy balance, also regulates processes associated with cancer, such as cell proliferation, apoptosis, cell migration, cell invasion, angiogenesis and inflammation." (PMID 35115550, 2022). "Inhibition of GHRL expression suppressed cancer cell activity, inhibited M2 polarization in macrophages and reduced invasiveness." (PMID 38752750, 2024). "A study of tumor stages revealed that GHRL in the middle and late-stage cancers was significantly higher expressed than in the early stages, suggesting a potential function for GHRL in cancer development and migration." (PMID 37469414, 2023). "Previous studies have shown that GHRL works in several key processes of cancer progression, such as cell proliferation, migration, and invasion." (PMID 35938042, 2022). "The action mechanism of GHRL in promoting or inhibiting cancer progression, however, is still unclear." (PMID 35938042, 2022). "GHRL can regulate whole-body metabolism via the ghrelin-signaling pathway in the hypothalamus and alter the metabolic activity of cancer and immune cells." (PMID 34235071, 2021). "Further studies with larger and more well-defined sample populations are warranted to verify the role of GHRL and GHSR polymorphisms in cancer." (PMID 25376984, 2014). "In addition, the role of GHRL seems to be crucial in cell proliferation, migration, and invasion, as well as in inflammation in many cancers." (PMID 34715892, 2021). "However, sample type, cancer stage, and worse survival were correlated to high GHRL expression." (PMID 37469414, 2023).
tumor (8 papers, 2022 to 2024). "Of the 24 tissue sections, proteins encoded by COL4A1, IGFBP3, and TIMP1 were slightly up-regulated in tumor tissues, while GHRL and GJA1 proteins were relatively down-regulated in tumor tissues than para-tumor tissues." (PMID 38273348, 2024). "Correlation analysis between GHRL and related genes and markers of immune cells in Tumor Immune Estimation Resource (TIMER2.0)." (PMID 37469414, 2023). "We examined GHRL expression in relation to sample type (healthy/primary tumor), tumor stage (stages 1–4), and H. pylori status by applying UALCAN." (PMID 37469414, 2023). "To study the significance and possible molecular mechanisms of GHRL expression in tumor development, we found the correlation between the GHRL expression and clinical–pathological features of GC in the KM plotter." (PMID 37469414, 2023). "When tumor extrasellar growth is present, the decision tree segregates NR patients from responders (CR and PR) using levels of GHRL expression with an accuracy of 71.3%." (PMID 35643771, 2022). "However, the possible mechanisms of GHRL about tumor development, the GHRL expression in different stages of GC Correa’ cascade, and immune engagement in GC has not been well understood before." (PMID 37469414, 2023). "Above all, GHRL played a key function in recruiting and modulating TILs in GC, and it is worth to continue investigating the molecular mechanism and function of GHRL in modulating the tumor microenvironment." (PMID 37469414, 2023). "This study uncovered the critical involvement of GHRL in GC, Correa’ cascade, and the possible mechanisms via which GHRL may regulate tumor-infiltrating immune cells." (PMID 37469414, 2023). "All studied parameters were associated with GC clinical stages, as their relative median values upregulated with stages (II, III, IV) except SMAD7 was associated with stage IV only and GHRL did not associate with tumor stages." (PMID 35449150, 2022). "Accordingly, the observed decrease in GHRL expression in GC patients led to assume that GHRL may function as the tumor suppressor." (PMID 35449150, 2022). "All studied parameters were associated with GC clinical stages except SMAD7 was associated with stage IV only (P = 0.005) and GHRL did not associate with tumor stages (P ˃ 0.05)." (PMID 35449150, 2022). "However, the possible function of GHRL in regulating tumor immunity and its clinical significance in GC are still unknown." (PMID 37469414, 2023). "Furthermore, we used R software to further analyze the dynamic changes in GHRL in different pathological stages of GC Correa’ cascade; the Tumor Immune Estimation Resource2.0 (TIMER2.0) was used to investigate the relationship of GHRL with immune-related cells in the tumor microenvironments." (PMID 37469414, 2023). "GHRL, KLF4, and DUSP5 expression levels were relatively lower in tumor tissues, whereas DSP, PERP, and MMP9 were highly expressed in tumor tissues." (PMID 38273348, 2024). "Considering all the models, a patient stratification based on the extrasellar growth of the tumor, sex, age and the expression of E-cadherin, GHRL, IN1-GHRL, DRD2, SSTR5 and PEBP1 is proposed, with accuracies that stand between 71 to 95%." (PMID 35643771, 2022). "In the analysis of integrated gene data, a noticeable correlation was found between the expression level of GHRL and the LNR of the tumor." (PMID 35938042, 2022). "SMAD7, HIF-1α gene, and HIF-1α protein may be jointly implicated in cancer development and prognosis, while SEC13, GHRL, and lncRNA GHRLOS may act as tumor suppressors." (PMID 35449150, 2022). "Interestingly, 34/88 5-HT+ PDAC ROIs were identified in seven of nine tumor bearing KPC mice compared to SST (n = 2), PP (n = 4), and GHRL (n = 5)." (PMID 35574446, 2022).
tumor (continued). "SMAD7, HIF-1α gene and HIF-1α protein may be jointly involved in tumor development and prognosis (act as oncogenic factors), while SEC13, GHRL, and lncRNA GHRLOS may act as tumor suppressor factors and thus could be considered as novel therapeutic targets for gastric cancer." (PMID 35449150, 2022).
metabolic disease (2 papers, 2020 to 2025). A congenital disorder (due to inherited enzyme abnormality) or acquired (due to failure of a metabolically important organ) disorder resulting from an abnormal metabolic process. "Several single nucleotide polymorphisms (SNPs) in GHRL gene have been associated with metabolic diseases." (PMID 32698854, 2020). "Since both LPL and GHRL are involved in energy metabolism, these findings suggest the potential for sex-based differences in the pathophysiology of metabolic diseases in humans." (PMID 41238731, 2025).
infection (1 paper, 2013). The state of being infected such as from the introduction of a foreign agent such as serum, vaccine, antigenic substance or organism. "Immunostaining confirmed these qRT-PCR findings and demonstrated that only RFP+ cells produced by Ad-RFP-Neurog3 infection were immunostained with antibodies recognizing NEUROD1, NKX2.2, CHGA, SST or GHRL." (PMID 24252877, 2013). "We fractionated cells produced by Ad-RFP-Neurog3 infection by RFP intensity and measured mRNA expression of Neurog3, CHGA, SST and GHRL by qRT-PCR." (PMID 24252877, 2013).